IKBIP (IKBKB interacting protein)
Synonyms: IKIP; FLJ31051
Tractability: Antibody: UniProt predicts a signal peptide or a membrane-spanning region. PROTAC: ubiquitination databases record sites on it; its protein half-life has been measured.
Gene: Protein-coding gene on chromosome 12 (98,613,405 to 98,645,113, reverse strand). Ensembl gene ENSG00000166130.
Subcellular location: Endoplasmic reticulum membrane
Subcellular location (Human Protein Atlas): Endoplasmic reticulum; Mitochondria; Nucleoli rim
Pathways (Reactome):
Immune System: Regulation of NF-kappa B signaling
Gene Ontology:
Molecular function: protein binding
Biological process: response to X-ray
Cellular component: endoplasmic reticulum; membrane; endoplasmic reticulum membrane
Genetic constraint (gnomAD): Loss-of-function variants: 20 observed, 22.45 expected, observed/expected ratio (o/e) 0.89, 90% interval 0.63 to 1.29. The upper end of that interval is the gene's LOEUF score, 1.29, which puts it in group 5 of 6, group 1 being the genes least tolerant of losing a copy. Missense variants: 366 observed, 355.19 expected, observed/expected ratio (o/e) 1.03, 90% interval 0.94 to 1.12. Synonymous variants: 135 observed, 133.01 expected, observed/expected ratio (o/e) 1.01, 90% interval 0.88 to 1.17.
Homologues: Orthologues: macaque IKBIP (94% identical), dog IKBIP (89% identical), pig IKBIP (88% identical), rabbit IKBIP (86% identical), chimpanzee IKBIP (86% identical), guinea pig IKBIP (81% identical), rat Ikbip (79% identical), mouse Ikbip (22% identical), zebrafish ikbip (16% identical).
Diseases named in the same sentence as IKBIP in open-access papers:
IKBIP is named in the same sentence as 14 diseases in open-access papers, as found by Europe PMC text mining. Sharing a sentence is not in itself a finding about the gene and the disease. The quoted sentences say what the papers report.
glioma (10 papers, 2021 to 2024). A benign or malignant brain and spinal cord tumor that arises from glial cells (astrocytes, oligodendrocytes, ependymal cells). "Overall, their findings are consistent that IKBIP is highly expressed in gliomas and is associated with significantly shorter patient survival." (PMID 36999060, 2023). "In conclusion, IKBIP expression was associated with more aggressive phenotypes of glioma and predicted much worse survival for patients." (PMID 33552590, 2021). "Gene ontology analysis demonstrated that IKBIP was profoundly associated with extracellular matrix organization, cell–substrate adhesion and response to wounding in both pan-glioma and glioblastoma." (PMID 33552590, 2021). "IKBIP was associated with more aggressive phenotypes of gliomas." (PMID 33552590, 2021). "In recent years, an increasing number of studies have shown that IKBIP can serve as a predictive biomarker for many cancers, such as glioma, renal cell carcinoma and gastrointestinal cancer." (PMID 38914958, 2024). "Knockdown of Gas2l3 expression in zebrafish embryos caused abnormal ventricle formation and brain dysmorphogenesis The expression of another DCA/CDCA regulated gene, IKBIP, showed positive correlation with glioma grade." (PMID 37259326, 2023). "IKBIP, while less characterized, has been postulated to interact with NF-kB signaling, a pathway with known implications in glioma progression and inflammation, possibly affecting microglial activation states." (PMID 38137116, 2023). "There are only a few articles on IKBIP as a predictive/prognostic biomarker, and all of them are about gliomas." (PMID 36999060, 2023). "In summary, we believe that hsa_circ_0072389, hsa_circ_0072386, hsa_circ_0008621, hsa_circ_0072387, and hsa_circ_0072391 induce the NF-κB and JAK/STAT pathways to aggravate glioma via miR-338-5p/IKBIP." (PMID 34897031, 2021). "Kaplan–Meier (KM) survival analyses were performed to examine the prognostic value of IKBIP in glioma." (PMID 33552590, 2021). "In the present study, we took advantage of 998 glioma patients with transcriptome data to investigate the clinical significance, molecular characterization and biological function of IKBIP in glioma." (PMID 33552590, 2021). "Then, Western blotting was used to determine the expression of IKBIP in U251 glioma cells and found that the expression of IKBIP protein was downregulated relative to that in the normal control group." (PMID 34897031, 2021). "Inhibitor of kappa B kinase interacting protein (IKBIP) has been reported to promote glioma progression, but its role in other cancers remains unclear." (PMID 38914958, 2024). "In the intricate landscape of glioma pathogenesis, the elucidation of risk scores derived from pivotal hub genes—RPL3, RPL12, PTEN, IFNGR2, KLF10, PLAUR, MSN, and IKBIP—emerged as a critical component in understanding the disease’s progression and patient stratification." (PMID 38137116, 2023). "According to previous study, IKBIP has only been shown to promote malignant progression of glioma." (PMID 37454079, 2023). "Moreover, higher IKBIP expression indicated a significantly shorter survival for patients with glioma, across different WHO grades." (PMID 33552590, 2021). "By analyzing genes related to IKBIP expression, possible pathways affecting glioma were identified." (PMID 34897031, 2021). "According to IKBIP expression, pan-glioma samples were divided into two groups in each data set." (PMID 33552590, 2021). "With the Pathcards and GEPIA databases, we inferred that IKBIP may promote the development of glioma NF-κB, JAK/STAT and TGFβ/SMAD signaling pathways." (PMID 34897031, 2021). "Understanding the molecular mechanism of IKBIP in glioma may provide a novel therapeutic target to overcome this fatal disease." (PMID 33552590, 2021). "Because genes play different roles in different cancers, we explored the pathways that may be affected by IKBIP in glioma by searching the pathcards and GEPIA databases." (PMID 34897031, 2021).
glioma (continued). "We found that IKBIP expression showed positive correlation with WHO grade of glioma." (PMID 33552590, 2021). "Furthermore, higher IKBIP expression was usually accompanied by a more aggressive and malignant phenotype in glioma, including GBM, IDH wild type and mesenchymal subtype." (PMID 33552590, 2021). "To verify the relationship among hsa_circ_0072389, hsa_circ_0072386, hsa_circ_0008621, hsa_circ_0072387, and hsa_circ_0072391 with IKBIP, we knocked down hsa_circ_0072389, hsa_circ_0072386, hsa_circ_0008621, hsa_circ_0072387, and hsa_circ_0072391 in U251 glioma cells separately." (PMID 34897031, 2021). "Based on these, we concluded that apart from being a key molecule for EMT induction, IKBIP might contribute as an immune suppressor in glioma as well, which further validated its oncogenic role in glioma." (PMID 33552590, 2021). "Additionally, IKBIP is critical for the development of glioma." (PMID 36999060, 2023). "Therefore, we speculated that IKBIP may induce the development of glioma through the NF-κB signaling pathway, JAK/STAT signaling pathway and TGFβ/SMAD signaling pathway." (PMID 34897031, 2021). "However, the role of IKBIP in glioma still remains largely unclear." (PMID 33552590, 2021). "Finally, higher IKBIP indicated significantly shorter survival for glioma patients." (PMID 33552590, 2021). "Moreover, by using the GEPIA, miRwalk, miRDB, and TargetScan databases and GSE4290, IKBIP was found to facilitate the development of glioma and may be inhibited by miR-338-5p, which induced us to establish a circRNA-miRNA-miRNA network." (PMID 34897031, 2021). "In the present study, we investigated the transcriptional expression profiles of IKBIP in 998 glioma patients and revealed that IKBIP expression showed significant positive correlation with the WHO grade of glioma." (PMID 33552590, 2021). "The correlation between IKBIP and these markers in GBM was also very robust in both data sets, indicating synergistic effects of these members during glioma EMT." (PMID 33552590, 2021). "In the GEPIA database, we found that IKBIP was upregulated in glioma relative to normal tissue, while CCBE1, NRG1, and RGS4 were downregulated in glioma." (PMID 34897031, 2021). "Therefore, we hypothesized that IKBIP was regulated by miR-338-5p in glioma." (PMID 34897031, 2021). "IKBIP was increased in isocitrate dehydrogenase (IDH) wild type and mesenchymal molecular subtype of glioma." (PMID 33552590, 2021). "Subsequent GSEA analysis revealed remarkable evidence because IKBIP was particularly correlated with EMT, which had been extensively confirmed to play a key role not only in glioma migration/invasion but also in glioma recurrence and therapeutic resistance." (PMID 33552590, 2021). "Then, the upregulation of IKBIP results in the activation of the NF-κB signaling pathway, JAK/STAT signaling pathway and TGFβ/SMAD signaling pathway, which worsen the deterioration of glioma." (PMID 34897031, 2021). "IKBIP, a novel marker of epithelial-mesenchymal transition (EMT) predicting poor prognosis in gliomas, was found to be expressed in blood vessels of all PitNETs and showed strong cytoplasmic positivity in PIT1 tumor cells and was essentially negative in tumor cells from SF1 and TPIT tumors." (PMID 34758873, 2021). "Besides, IKBIP seemed to be more associated with neutrophil-mediated immunity, suggesting that IKBIP upregulation was accompanied by immunosuppression of GBM, which indicated a more malignant characteristic in glioma." (PMID 33552590, 2021). "Furthermore, IKBIP was significantly involved in EMT and could serve as an independent prognosticator in glioma." (PMID 33552590, 2021). "However, although these screened genes of 8 common cancer-related pathways may be correlated with IKBIP, they may not affect glioma; therefore, we further performed survival analysis of these genes in glioma by using the GEPIA database." (PMID 34897031, 2021).
glioblastoma (4 papers, 2021 to 2024). The most malignant astrocytic tumor (WHO grade IV). "Applying Reboot on data from 154 glioblastoma patients, we identified a three-gene signature (IKBIP, OSMR, PODNL1) whose increased derived risk score was significantly associated with worse patients’ prognosis." (PMID 34316711, 2021). "Additionally, IKBIP has been reported to maintain the abnormal proliferation of glioblastoma cells by inhibiting the degradation of CDK4." (PMID 38914958, 2024). "Importantly, a growing number of studies have shown that IKBIP may serve as a predictive biomarker and a potential therapeutic target for several cancers, such as glioblastoma, renal cancer and lung cancer." (PMID 38914958, 2024). "At present, the functional exploration of IKBIP is limited to glioblastoma and has not been studied in detail in other cancers." (PMID 38914958, 2024).
Fanconi anemia (1 paper, 2023). Fanconi anemia (FA) is a hereditary DNA repair disorder characterized by progressive pancytopenia with bone marrow failure, variable congenital malformations and predisposition to develop hematological or solid tumors.
Obesity (1 paper, 2023). Accumulation of substantial excess body fat. "The abundance of different obesity related proteins such as LEP, ITGAL, IKBIP, H2-AA, TAP2 and FABP5 was very low in AdEVs from lean mice and was detected in only one or no biological replicate." (PMID 36759608, 2023).
oesophageal cancer (1 paper, 2023). "The top GPR176-correlated genes (PDPH, KIREL1, CLEC12A-AS1, CERCAM, IKBIP, LOX, COL5A2 and ELF3) were more highly expressed in oesophageal cancer than in normal tissue (p < 0.05), but the converse was true for C9orf152 and MT-TP (p < 0.05)." (PMID 37584712, 2023).
papillary renal cell carcinoma (1 paper, 2023). A rare subtype of renal cell carcinoma, arising from the renal tubular epithelium and showing a papillary growth pattern, which typically manifests with hematuria, flank pain, palpable abdominal mass or nonspecific symptoms, such as fatigue, weight loss or fever. "In other malignant tumors, few reports have examined the function of IKBIP, especially in papillary renal cell carcinoma." (PMID 37454079, 2023). "And our results revealed that IKBIP mRNA expression was up-regulated in papillary renal cell carcinoma than in its corresponding normal tissues." (PMID 37454079, 2023). "Besides, Multivariate analysis indicated that IKBIP mRNA expression was an independent prognostic factor for patients of papillary renal cell carcinoma." (PMID 37454079, 2023). "Moreover, High IKBIP mRNA expression was negatively correlated with overall survival (OS) and disease-free survival (DFS) in patients of papillary renal cell carcinoma." (PMID 37454079, 2023).
tumor (8 papers, 2021 to 2024). "IKBIP expression was significantly associated with tumor length (p = 0.028), N stage (p < 0.001), and pTNM stage (p < 0.001)." (PMID 38914958, 2024). "IKBIP expression levels were associated with tumor immune invasion and IKBIP-targeted drugs, and IKBIP was found to be positively or negatively correlated with TMB and MSI in various malignancies." (PMID 36999060, 2023). "Our findings imply that IKBIP expression is strongly associated with tumor immune infiltration, which influences patient prognosis and offers a potential immunotherapeutic target for the treatment of patients with various cancers." (PMID 36999060, 2023). "We looked at possible relationships between the expression of IKBIP and various immune-related genes, immune infiltration levels, tumor mutational burden (TMB), microsatellite instability (MSI), and the TME." (PMID 36999060, 2023). "G and H. Representative images of Ki-67 expression in tumor samples from the IKBIP-overexpressing (G) group or IKBIP-knockdown group (H)." (PMID 38914958, 2024). "C and D. The tumor nodules were isolated (C) and weighed (D) from the IKBIP-knockdown group and paired control group mice." (PMID 38914958, 2024). "For this reason, we analyzed the IKBIP mRNA expression differences between ESCC tumor tissues and normal tissues through multiple bioinformatics databases, and found that IKBIP expression was significantly up-regulated in ESCC tissues." (PMID 38914958, 2024). "The results showed that IKBIP expression was closely correlated with cancer stage, N stage and tumor differentiation grade, which was consistent with the results of the IHC-based clinicopathological analysis." (PMID 38914958, 2024). "Our results revealed that IKBIP functions as a tumor promoter in ESCC and provides a new therapeutic target for ESCC." (PMID 38914958, 2024). "In summary, we revealed the potential of IKBIP as a biomarker for predicting ESCC and the role of IKBIP in promoting tumor development in ESCC." (PMID 38914958, 2024). "An in vivo study indicated that IKBIP overexpression promoted tumorigenesis and tumor growth in xenograft models established with lentivirus-transfected ESCC cells." (PMID 38914958, 2024). "The tumor growth curve showed a significantly faster tumor growth trend in mice after IKBIP overexpression, while the IKBIP-knockdown group had a slower tumor growth trend." (PMID 38914958, 2024). "The Ki-67 expression in the tumor tissues of the IKBIP-overexpressing group was significantly greater than that in the tumor tissues of the vector group, whereas Ki-67 expression in the IKBIP-knockdown group was significantly greater than that in the NC group." (PMID 38914958, 2024). "A and B. The tumor nodules were isolated from the IKBIP-overexpressing group and the corresponding control group (A), and the tumor nodules were weighed (B)." (PMID 38914958, 2024). "In contrast, tumor growth in the IKBIP-knockdown group was significantly inhibited compared to that in the matched control group." (PMID 38914958, 2024). "(B) GEPIA2 database based on TCGA-ESCA samples showed the mRNA expression of IKBIP was higher in tumor tissues than normal tissues." (PMID 38914958, 2024). "E and F. The tumor growth curves were plotted according to the tumor volume of mice in the IKBIP-overexpressing group (E) or IKBIP knockdown group (F)." (PMID 38914958, 2024). "In vivo experiments revealed larger tumor sizes and greater tumor weights in the IKBIP-overexpressing group than in the vector group." (PMID 38914958, 2024). "B and C. The expression of IKBIP at different nodal metastasis stages (N0-N3) and tumor differentiation stages (grades 1–3) in ESCA is shown." (PMID 38914958, 2024). "This suggests that methylation is an important way for IKBIP to exert its biological effects, and that methylation patterns differ in different tumor tissues, including hypomethylation and hypermethylation." (PMID 36999060, 2023).